VWF (von Willebrand factor)
Diseases named in the same sentence as VWF in open-access papers (continued):
Sharing a sentence is not in itself a finding about the gene and the disease.
tumor (continued). "VWF, a complex plasma glycoprotein that facilitates platelet attachment to the endothelium, plays a pivotal role in hemostasis, tumor progression, and metastasis." (PMID 37953280, 2023). "Apart from angiogenesis, the induction of tumor–endothelial adhesion and pulmonary leakiness by vWF‐SAM‐sEVs was also suppressed by anti‐VEGF‐A and anti‐FGF2 antibodies." (PMID 37387563, 2023). "At a paradox to the evidence supporting a pro-metastatic role for VWF, there is evidence to suggest that VWF also plays a role in inhibiting tumor angiogenesis and promoting apoptosis." (PMID 35327035, 2022). "RNA-Seq- or qRT-PCR-based quantification of prognostically significant transcripts (e.g., VWF or MRTG.153013.3) in MCL tumor tissues during routine clinical evaluations can potentially be used to improve prognostication of MCL cases during diagnosis." (PMID 36359790, 2022). "VWF has also been identified as a potential circulating marker for tumour angiogenesis in other types of cancer." (PMID 35052804, 2022). "ALPL, APOL6, SON, and VWF proteins were significantly differentially expressed between normal and tumor tissues." (PMID 35991564, 2022). "For example, the collagen-binding domain of von Willebrand Factor fused to checkpoint inhibitor antibodies can concentrate therapy effects towards the fibrotic stroma of the tumor microenvironment." (PMID 35456962, 2022). "The GEPIA results showed that SERPINE1, ANXA5, F2R, and VWF increased significantly in tumor tissue." (PMID 36105100, 2022). "Upon tumor–induced endothelial cell activationthe vWF within WPB is secreted into the lumen of the blood vessel as well as basolaterally into the subendothelium." (PMID 35814405, 2022). "Apart from its more established roles underpinning hemostasis, VWF has more recently sparked interest for its potential role in tumor biology, including inflammation, angiogenesis and metastasis." (PMID 35327035, 2022). "While it is unclear at this stage as to what level the tumor-derived VWF contribute to systemic plasma VWF levels, it is likely that local VWF secretion provides a survival advantage to the neoplastic process." (PMID 35327035, 2022). "Interestinglyinhibition of GPIb–IX–V or vWF function reduced platelet–cancer cell interactions suggesting that these receptors play a role in tumor–induced platelet aggregation." (PMID 35814405, 2022). "There is emerging evidence to suggest VWF also plays a role in inflammation, angiogenesis and tumor biology, and it is likely that VWF promotes tumor metastasis." (PMID 35327035, 2022). "GP5, a part of the receptor for von Willebrand factor, has been poorly studied in tumor and disease diagnosis." (PMID 36404333, 2022). "Clustered stromal cells corresponded to endothelial cells (positive for PECAM1/CD31, VWF), normal fibroblasts (FN1, EGFL6), tumor-associated fibroblasts (TAFs; PDGFRA, ADH1B), and thymic epithelial cells (TECs; KRT19, S100A14)." (PMID 35869073, 2022). "VWF can facilitate tumor cell adhesion to endothelial cells and aids with the recruitment of platelets into the tumor microenvironment, where tumor/platelet aggregates are able to form and facilitate hematogenous spread of cancer." (PMID 35327035, 2022). "This tumor-mediated VWF secretion is via tumor secretomes acting on neighboring endothelial cells, including inflammatory cytokines, matrix metalloproteinases, and pro-angiogenic mediators such as VEGF-A (vascular endothelial growth factor A)." (PMID 35327035, 2022). "There is also evidence demonstrating that VWF is released from both tumor cells as well as the tumor microenvironment in certain cancer patients, in addition to the VWF released from the usual sources of endothelial cells and megakaryocytes." (PMID 35327035, 2022).
tumor (continued). "Tumor cells can induce endothelial cells to release VWF and certain tumor cells have the capacity for de novo expression of VWF, leading to a proinflammatory microenvironment that is likely conducive to tumor progression, metastasis and micro-thrombosis." (PMID 35327035, 2022). "Increased ADP expression from malignant cells, increased von Willebrand factor production, and tumor-induced thrombin are some of the main mechanisms involved in platelet activation due to malignancy." (PMID 36010924, 2022). "In vitro studies also demonstrate that there is reduced tumor migration when a tumor-derived VWF is inhibited in HCC." (PMID 35327035, 2022). "In fact, tumor cells are also thought to create a microenvironment rich in VWF by inducing the localized deposition of the VWF." (PMID 35327035, 2022). "There are a number of studies supporting the idea that VWF facilitates tumor adhesion to endothelial cells." (PMID 35327035, 2022). "For instance, in one of the models, a large panCK+ tumor cell cluster is visible inside a blood vessel that is positive for vWF, CD31 and vimentin." (PMID 35121992, 2022). "In the present study, compared with PA, VEGF expression in RPA or CXPA tended to increase or increased significantly, and the increase in small microvessels in the tumor tissue was confirmed in the cross-sections from patients with CXPA by vWF immunostaining." (PMID 34884420, 2021). "It is known that VWF binds to tumour cells via GPIIb/IIIa receptor and its hemi-identical twin, αvβ3 integrin [30,]." (PMID 33571850, 2021). "Tumour cells trigger platelets aggregation by binding to VWF (von Willebrand factor) and stimulating the VEGF secretion to support angiogenesis." (PMID 34975909, 2021). "This suggests that tumour-expressed ADAM28 inactivates VWF within the circulation, potentially favouring tumour cell survival within the vasculature, thus promoting cancer dissemination." (PMID 33571850, 2021). "A series of inhibition studies convincingly showed that tumor cell-derived tissue factor (TF) initiates thrombin generation which can subsequently lead to VWF secretion from the endothelium." (PMID 34572000, 2021). "Tumor cells use VWF to support their metastatic potential and hide from immune cells by cloaking themselves with VWF and platelets." (PMID 34572000, 2021). "Critically, these VWF multimers serve as a molecular bridge, facilitating the adhesion and aggregation of platelets and tumour cells along the endothelium, promoting transendothelial migration and subsequently cancer dissemination." (PMID 33571850, 2021). "Here, VWF can function as an adhesive anchor for tumor cells to facilitate docking to the endothelium and subsequent extravasation." (PMID 34572000, 2021). "This leads to the elimination of the proapoptotic effect of VWF and promotes the proliferation of tumor cells." (PMID 34046336, 2021). "The shear forces of the turbulent blood flow in the tortuous and leaky tumor vessels change the conformation of vWF and enable its recognition by the GPIb-complex." (PMID 33937274, 2021). "Growing evidence demonstrates that tumour cells not only induce the release of VWF multimers from endothelial cells, but also utilise VWF to adhere to the endothelium." (PMID 33571850, 2021). "Collectively, the ultra-large VWF binds to the platelet GPIbα and GPIIb/IIIa receptors, and at the same time adheres to tumour cells via GPIIb/IIIa receptor and αvβ3 integrin, to facilitate the metastatic process." (PMID 33571850, 2021). "Recently, more and more studies have shown that tumor cells can also acquire the ability to synthesize VWF de novo." (PMID 34572000, 2021). "No significant changes were observed in the plasma levels of VWF at the early phases of metastasis, specifically in the first and second week after tumour cell inoculation in the 4T1 murine model, when only micrometastases were detected." (PMID 33571850, 2021).
tumor (continued). "As can be seen in the vWF immunostainings, compared to PA, denser small microvessels were found in the tumor tissue from the cross-sections of patients with CXPA and RPA." (PMID 34884420, 2021). "Recently, von Willebrand factor (VWF), a haemostatic plasma glycoprotein, has been shown to play an important role in tumour progression and metastasis." (PMID 33571850, 2021). "This resistance of VWF-mediated apoptosis was dependent on tumour cell expression of a specific metalloproteinase ADAM28 that cleaves VWF, rendering its apoptotic function inactive." (PMID 33571850, 2021). "An increased VWF level observed in the clinical setting is an indicator of endothelial damage and is often considered as a factor contributing to tumor progression." (PMID 34046336, 2021). "Molecular targets in tumors, such as exposed collagen, were used to create Rexin-G, which uses a von Willebrand factor (vWF) to modify the virus envelope and thus target tumor and metastatic niches when injected intravenously." (PMID 34502287, 2021). "The rise in the VWF antigen in cancer patients has been attributed to tumor-induced activation of the endothelium which promotes cancer cell intravasation into the circulation." (PMID 34572000, 2021). "In fact, plasmatic levels of VWF have been proposed as prognostic markers in patients with solid cancer, including those with HCC, in whom high levels of VWF have been correlated with increased rates of tumor recurrence after treatments." (PMID 33800224, 2021). "In vivo animal experiments have shown that NETs capture tumor cells and bind them to vascular walls via von Willebrand factor (VWF)." (PMID 34204148, 2021). "On the other hand, VWF binds to tumour cells via GPIIb/IIIa receptor or its hemi-identical twin αvβ3 integrin, thereby facilitating the extravasation of cancer cells through the activated endothelium." (PMID 33571850, 2021). "In general, healthy ECs and tumor-derived ECs were positive for all tested markers except for CD34 (VWF+, ACE+, CD31+, CD133+, CD105+), but pathological ECs were characterized by lower levels of expression." (PMID 34445568, 2021). "Plasmatic VWF has further been shown to be a biomarker for tumor progression as VWF levels are increased in cancer patients with tumors of multiple origins." (PMID 34572000, 2021). "The action of VEGF in neoplastic disease leads to enhanced TF expression by endothelial cells and increased release of vWF." (PMID 33146401, 2021). "A recent study also found high vWF expression in tumor cells, contributing to a significant elevation of vWF levels in cancer patients." (PMID 33292287, 2020). "Tumor vasculature, visualized using the endothelial markers von Willebrand factor and CD34, revealed relatively low TAMRA-FP signal originating from endothelial cells." (PMID 32190011, 2020). "Pro-inflammatory cytokines [i.e., TNF-α and interleukin (IL)-1β] and pro-angiogenic factors (i.e., VEGF) released by tumor cells induce the overexpression of TF by endothelial cells and monocytes and the release of vWF by endothelial cells." (PMID 33042789, 2020). "The expression of P-selectin and the activated GPIIb/IIIa complex, as well as the binding of vWF and fibrinogen on the platelet surface increased significantly every week from t0 to the fifth week of tumor progression." (PMID 32191918, 2020). "Nevertheless, it is already known that vWF levels are elevated in the blood of patients with malignant breast cancer and that these levels correlate with tumor progression." (PMID 32191918, 2020). "The von Willebrand factor (VWF) is a multimeric glycoprotein and plays an essential role in mediating platelet-tumor cell interactions." (PMID 33062704, 2020). "Shear-sensitive anti-thrombotic therapy has promising future owing to the shear stress-dependent interaction of platelet receptor GPIBα with the A1 domain of VWF.Aim at circulating tumour cell.Synthesis of hybrid membrane." (PMID 32793380, 2020).
tumor (continued). "Cancer cells promote the secretion of WPBs and vWF from ECs and elevated plasmatic vWF correlate with tumor grade and metastasis." (PMID 33365273, 2020). "In this study, RAGE-aptamer injection significantly suppressed tumor-associated angiogenesis evaluated by CD31 and vWF expression in association with the reduction of VEGF levels in the G361 tumors." (PMID 31565056, 2019). "We determined the relationship of tumor volume and stage with the VWF:Ag/ADAMTS13:AC ratio and AFP-L3%." (PMID 31638892, 2019). "They further showed that the combination of VWF release and decreased local ADAMTS‐13 in the tumor tissue is likely to cause a procoagulatory milieu." (PMID 31294335, 2019). "The von Willebrand factor: Ag/ADAMTS13:AC ratio was exclusively correlated with tumor volume and stage as well as serum vascular endothelial growth factor levels." (PMID 31638892, 2019). "The number of tumour microvessels, identified by the von-Willebrand factor (vWF) staining, was observed to have decreased significantly 72 h after treatment." (PMID 31239493, 2019). "Endothelial integrity disruption also exposes extracellular matrix proteins such as von Willebrand factor (vWF), collagen, or fibronectin, which in turn, recruit and activate platelets that act in concert to further tune tumor cell intravasation." (PMID 31623163, 2019). "In turn, high expression of vWF in primary tumours is compatible with the notion that vWF is required in the initial phase of metastatic foci formation, independent of its role in haemostasis." (PMID 30683749, 2019). "To verify the IR-induced morphological microvascular changes, we examined the molecular phenotypes of the tumor vessels by immunofluorescence staining with the additional endothelial cell markers CD34 and VWF during each stage of tumor progression." (PMID 31803626, 2019). "Tumor volume and stage significantly correlated with the VWF:Ag/ADAMTS13:AC ratio (p = 0.0002 and p = 0.046, respectively) but not with the AFP-L3%." (PMID 31638892, 2019). "Positive immunoreactivity to antibodies against the endothelial cell marker proteins CD31 and von Willebrand Factor (vWF) confirmed the endothelial differentiation of the tumour cells." (PMID 29731980, 2018). "In the aortic endothelium of tumour-bearing mice, vWF expression was increased compared to control animals." (PMID 29788918, 2018). "Of note, vWF was suggested as the important mediator of platelet–tumor cells interactions, thereby promoting metastasis." (PMID 30279208, 2018). "Emerging roles of vWF involved in cancer cell biology, especially in tumor metastasis, were also identified in many types of human cancers." (PMID 30279208, 2018). "Due to the low flow, growth factors, and cytokines released from the tumor cells, endothelial cells expose TF on their surface and release von Willebrand factor (vWF) and plasminogen activator inhibitor (PAI-1)." (PMID 30180930, 2018). "Consistent with the enhanced pulmonary grafts of BGC823 cells, the ratio of the tumor-bearing area to the total lung area was higher in mice receiving vWF-overexpressing cells than in those receiving sham-transfected cells." (PMID 29362409, 2018). "Additionally, some tumor patients suffering from various kinds of cancer are deficient in enzymes cleaving von Willebrand factor (vWf), which could finally lead to a platelet activation by highly polymeric forms of vWf in the circulation and enhanced number of metastases." (PMID 30305116, 2018). "In mice derived tumors, we observed the presence of human vessels infiltrating the tumor as HLA/VWF expressing cells, suggesting an endothelial differentiation of CD105+ CSC." (PMID 29854307, 2018). "All of antibodies have a potential effect on inhibition of tumor metastasis by affecting the collagen, vWF, and GPIbα interaction via binding to GPIbα aa 41-50 and aa 277-290, respectively." (PMID 30223883, 2018). "The results demonstrated approximately 1.8 to 6.7% VWF expressing cancer cells in these tumor biopsies." (PMID 28035064, 2017).
tumor (continued). "We investigated the expression of vWF in LAC through immunohistochemical staining of tumor tissue microarrays (TMAs)." (PMID 29299165, 2017). "We also performed immunohistochemistry analyses to detect and quantify VWF expressing cancer cells in these tumor biopsy samples." (PMID 28035064, 2017). "Immunohistochemical staining of these tumors for von Willebrand factor (vWF), an endothelial cell marker, was used to visualize the tumor blood vessels." (PMID 28415573, 2017). "We found that vWF was overexpressed preferentially in the tumor vasculature of LAC compared with the adjacent tissue vasculature." (PMID 29299165, 2017). "Tumor cell-derived factors promote vWF expression in ECs through increased binding of the transcription factor GATA3." (PMID 29299165, 2017). "Here, we show that vascular and lymphatic endothelial cells (ECs) express VWF in vitro and release VWF fibers after activation by tumor cell supernatants." (PMID 27602496, 2016). "Consistently, the density of von Willebrand factor (vWF) immunostaining is decreased in the Foxp3-knokcking down tumor xenografts, as compared with the control (p = 0.020)." (PMID 27557492, 2016). "Treatment with Tinzaparin inhibited tumor-induced release of VWF multimers, impeded platelet aggregation and decreased lung metastasis." (PMID 27602496, 2016). "For example, 71 ± 10.1% of very large tumor vessels (> 100 μm), but only 10.1 ± 3.0% of small vessels (10 μm-30 μm), exhibited intraluminal VWF fibers." (PMID 27602496, 2016). "In summary, VWF expression and intraluminal VWF fiber formation are scarcely present in healthy lymphatic vessels and tumor lymphatics." (PMID 27602496, 2016). "To answer this question, we analyzed 62 lymphatic vessels in healthy skin as control and 80 intratumoral lymphatic vessels in primary Ret tumor cryosections stained for VWF and Lyve-1." (PMID 27602496, 2016). "Thrombin activates platelets, which are critical mediators of tumor cell implantation and serve as bridges to the endothelial surface through the highly adhesive VWF." (PMID 27602496, 2016). "In contrast, the tumor microvasculature exhibited VWF fibers in the blood vessel lumina, correlating with a strong reduction in VWF stored in the endothelium." (PMID 27602496, 2016). "In this study, we report that the tumor microenvironment promotes EC activation, as reflected by intraluminal VWF fibers present in the tumor microvasculature and in tumor-free distal organs." (PMID 27602496, 2016). "By contrast, inhibition of thrombin and VEGF-A by the LMWH Tinzaparin is required for an efficient blockage of EC activation and VWF fiber formation in the tumor vasculature." (PMID 27602496, 2016). "Recently, VWF has been considered a potential circulating marker for tumor angiogenesis in different types of cancer." (PMID 27236861, 2016). "In the healthy lungs of tumor-free mice, 19.1 ± 3.8% of the vessels exhibited intraluminal VWF networks." (PMID 27602496, 2016). "Interestingly, the impaired proliferation of tumor cells transduced with shPKM2 was associated with decreased blood vessel formation of both intratumoral and extratumoral origin/vessels as revealed by reduced immunoreactivity of von Willebrand Factor (vWF) and desmin." (PMID 26739387, 2016). "Tinzaparin, a clinically approved low-molecular-weight heparin (LMWH), causes inhibition of EC activation and subsequent attenuation of VWF network formation and platelet aggregation, thus resulting in a tumor weight reduction and survival benefits." (PMID 27602496, 2016). "To evaluate the role of VWF fibers on primary tumor growth, we analyzed tumor growth in wild type (WT) mice, VWF−/− and ADAMTS13−/− mice." (PMID 27602496, 2016). "Detailed histopathological analysis revealed that Stat3-deficient murine tumours were better vascularized at all investigated time points, which was corroborated by increased CD31+ and von Willebrand Factor staining of vessel walls." (PMID 25734337, 2015).